PTPRS (protein tyrosine phosphatase receptor type S)
Description:
Cell surface receptor that binds to glycosaminoglycans, including chondroitin sulfate proteoglycans and heparan sulfate proteoglycan. Binding to chondroitin sulfate and heparan sulfate proteoglycans has opposite effects on PTPRS oligomerization and regulation of neurite outgrowth. Contributes to the inhibition of neurite and axonal outgrowth by chondroitin sulfate proteoglycans, also after nerve transection. Plays a role in stimulating neurite outgrowth in response to the heparan sulfate proteoglycan GPC2. Required for normal brain development, especially for normal development of the pituitary gland and the olfactory bulb. Functions as a tyrosine phosphatase. Mediates dephosphorylation of NTRK1, NTRK2 and NTRK3 (By similarity). Plays a role in down-regulation of signaling cascades that lead to the activation of Akt and MAP kinases (By similarity). Down-regulates TLR9-mediated activation of NF-kappa-B, as well as production of TNF, interferon alpha and interferon beta.
Synonyms: R-PTP-S; R-PTP-sigma; PTPsigma; PTP-sigma
Tractability: Small molecule: a structure with a bound ligand is known; a high-quality ligand is known; it belongs to a druggable protein family. Antibody: UniProt places it where antibodies can reach, with high confidence; its Gene Ontology location is reachable by antibodies, with high confidence; UniProt predicts a signal peptide or a membrane-spanning region. PROTAC: ubiquitination databases record sites on it; its protein half-life has been measured; a small molecule that binds it is known.
Target class: Enzyme; Protein Phosphatase; Receptor tyrosine-protein phosphatase; Tyrosine protein phosphatase; Phosphatase
Gene: Protein-coding gene on chromosome 19 (5,158,495 to 5,340,941, reverse strand). Ensembl gene ENSG00000105426.
Subcellular location: Cell membrane; Cell projection, axon; Perikaryon; Cytoplasmic vesicle, secretory vesicle, synaptic vesicle membrane; Synapse, synaptosome; Postsynaptic density; Cell projection, neuron projection; Cell projection, growth cone
Subcellular location (Human Protein Atlas): Cytosol; Plasma membrane; Predicted to be secreted
Pathways (Reactome):
Neuronal System: Receptor-type tyrosine-protein phosphatases; Synaptic adhesion-like molecules
Extracellular matrix organization: ECM proteoglycans
Signal Transduction: Signaling by NTRK3 (TRKC)
Gene Ontology:
Molecular function: phosphoprotein phosphatase activity; protein binding; protein tyrosine phosphatase activity; chondroitin sulfate binding; heparan sulfate proteoglycan binding; heparin binding
Biological process: negative regulation of interferon-alpha production; negative regulation of interferon-beta production; negative regulation of toll-like receptor 9 signaling pathway; protein dephosphorylation; synaptic membrane adhesion; negative regulation of axon extension; negative regulation of axon regeneration; negative regulation of collateral sprouting; negative regulation of dendritic spine development; negative regulation of neuron projection development; peptidyl-tyrosine dephosphorylation; signal transduction; modulation of chemical synaptic transmission; regulation of postsynaptic density assembly; synapse organization; trans-synaptic signaling
Cellular component: extracellular exosome; plasma membrane; axon; perikaryon; postsynaptic density; postsynaptic density membrane; synaptic vesicle membrane; glutamatergic synapse; growth cone; neuron projection; presynaptic membrane; Schaffer collateral - CA1 synapse; synapse
Genetic constraint (gnomAD): Loss-of-function variants: 60 observed, 196.6 expected, observed/expected ratio (o/e) 0.31, 90% interval 0.25 to 0.38. The synonymous counts are far from expectation, so gnomAD's model fits this gene poorly and the ratio says little. Missense variants: 2,249 observed, 2,706.8 expected, observed/expected ratio (o/e) 0.83, 90% interval 0.8 to 0.86. Synonymous variants: 1,395 observed, 1,155.4 expected, observed/expected ratio (o/e) 1.21, 90% interval 1.15 to 1.26.
Homologues: Orthologues: chimpanzee PTPRS (99% identical), macaque PTPRS (99% identical), pig PTPRS (97% identical), dog PTPRS (96% identical), rat Ptprs (92% identical), mouse Ptprs (92% identical), guinea pig PTPRS (85% identical). Paralogues in human: PTPRD (71% identical), PTPRF (66% identical), PTPRK (22% identical), PTPRM (22% identical), PTPRZ1 (22% identical), PTPRT (21% identical), PTPRU (21% identical), PTPRG (20% identical), PTPRA (18% identical), PTPRB (17% identical), PTPRE (16% identical), PTPRC (16% identical), and 23 more.
Diseases named in the same sentence as PTPRS in open-access papers:
PTPRS is named in the same sentence as 65 diseases in open-access papers, as found by Europe PMC text mining. Sharing a sentence is not in itself a finding about the gene and the disease. The quoted sentences say what the papers report.
colorectal cancer (9 papers, 2008 to 2025). A primary or metastatic malignant neoplasm that affects the colon or rectum. "Mutation or deletion of PTPRS has been reported in several human cancers, including head and neck squamous cell carcinoma, colorectal cancer, malignant melanoma and cholangiocarcinoma." (PMID 37175550, 2023). "PTPRS was reported also as a tumor suppressor in several cancers, and also the deletion or mutation of PTPRS was detected in several types of cancer such as colorectal cancer, head and neck squamous-cell carcinoma, and CCA." (PMID 35991009, 2022). "PTPRS is the most commonly mutated receptor tyrosine phosphatase in colorectal cancer (CRC)." (PMID 31827720, 2019). "For example, a 3-mm TA harbored one of the highest MB of 6.45, with pathogenic mutational defects in numerous colorectal cancer driver genes (e.g., APC, SOX9, TCF7L2, ASXL1, ERBB3, MAP2K1, and PTPRS)." (PMID 40757636, 2025). "PTPRS has been reported to negatively regulate the RAS pathway in colorectal cancer (CRC) by dephosphorylating Erk, leading to its deactivation and preventing its nuclear translocation." (PMID 40394416, 2025). "Approximately 10% of colorectal cancers harbor native mutations in PTPRS, and inactivation of PTPRS promotes ERK and AKT activation, resulting in enhanced RAS and EGFR activity in colorectal cancer." (PMID 34805171, 2021). "Whereas, in colorectal cancer PTPRS regulated RAS pathway activity by inactivating ERK and preventing its nuclear translocation." (PMID 33163494, 2020). "Protein tyrosine phosphatase receptor S (PTPRS), a tumor suppressor previously reported in colorectal cancer, hepatocellular carcinoma and head and neck cancer, is thought to mediate cell migration and invasion by downregulation of EMT." (PMID 33163494, 2020). "Our results provide evidence for frameshift mutations in six of these PTP genes (PTPN21, PTPRS, PTPN5, PTPN23, PTPRA, PTPRE) affecting about 32% of MSI-H colorectal cancers." (PMID 19000305, 2008). "In colorectal cancer, PTPRS negatively regulates the RAS pathway, so the decrease of PTPRS in cell lines increased the ERK activity." (PMID 35991009, 2022). "Our study revealed that inactivation of PTPRS enhanced the activation of ERK and AKT, which may facilitate the development of effective targeted therapies against ERK and/or AKT in colorectal cancer." (PMID 29915291, 2018).
Arthritis (4 papers, 2020 to 2025). Inflammation of a joint. "In previous studies, we demonstrated that soluble PTPRS Ig1&2 reduced arthritis severity in multiple mouse models." (PMID 40651610, 2025). "We further demonstrated that Ig1&2 suppresses arthritis in a PTPRS-specific manner in the K/BxN serum transfer-induced arthritis (STIA) model." (PMID 41026530, 2025). "Another transmembrane protein, PTPRS is highly enriched in RA and experimental arthritis synovial lining fibroblasts." (PMID 35252279, 2022). "For example, the receptor tyrosine phosphatase sigma (PTPRS) activating decoy protein attenuated severity of arthritis when combined with low dose of a TNF inhibitor, but was insufficient in itself to have an effect." (PMID 33390996, 2020). "Furthermore, soluble recombinant Ig1&2 can act as a decoy receptor to inhibit PTPRS expressed by fibroblasts binding to PG, thereby be used to treat arthritis." (PMID 35252279, 2022).
head and neck cancer (4 papers, 2018 to 2022). A primary or metastatic malignant neoplasm affecting the head and neck. "In head and neck cancer, loss of PTPRS promoted EGFR activity in the EGFR/phosphoinositide 3 kinase (PI3K) pathway." (PMID 35991009, 2022). "Furthermore, PTPRS was shown to dephosphorylate EGFR in A431 cells, and genomic analysis revealed frequent mutations of PTPRS in head and neck cancer." (PMID 31827720, 2019). "Related to our results, an association of high expression of PTPRS in tumor tissues with the longer OS of patients has been reported in HCC, head and neck cancer, and malignant peripheral nerve sheath tumor." (PMID 35991009, 2022). "In hepatocellular carcinoma and head and neck cancer, PTPRS regulated EGFR in EMT processes and drug resistance." (PMID 33163494, 2020). "PTPRS–EGFR interactions also played a vital role in chemotherapy resistance in head and neck cancer." (PMID 33163494, 2020).
hepatocellular carcinoma (4 papers, 2016 to 2022). A malignant tumor that arises from hepatocytes. "The low PTPRS expression was associated with LN metastasis, which was similar to hepatocellular carcinoma (HCC)." (PMID 35991009, 2022). "Our research team previously identified PTPRS regulated EMT via dephosphorylation of EGFR in hepatocellular carcinoma." (PMID 33163494, 2020). "PTPRS has also been postulated to act as a metastatic suppressor and shown to have reduced expression in 80% of hepatocellular carcinoma (HCC)." (PMID 31827720, 2019).
melanoma (3 papers, 2014 to 2023). A malignant, usually aggressive tumor composed of atypical, neoplastic melanocytes. "Loss of terminal differentiation traits, as observed by inactivation of ESR1, PTPRS, or the metastasis suppressor gene GATA3, may reflect the intrinsic capacity of melanoma cells to gain plasticity, and to progressively acquire changes that trigger metastatic dissemination." (PMID 28578692, 2017).
Alzheimer disease (2 papers, 2024 to 2025). A progressive, neurodegenerative disease characterized by loss of function and death of nerve cells in several areas of the brain leading to loss of cognitive function such as memory and language. "The soluble ectodomain has been implicated as a decoy for ligand–receptor interactions in PTPRS signaling, with potential therapeutic applications in diseases such as cancer, Alzheimer’s disease, stroke, traumatic brain injury, and rheumatoid arthritis." (PMID 40943264, 2025). "PTPRS activity has been implicated in various diseases, including traumatic brain injuries, Alzheimer’s disease, stroke, multiple sclerosis, bone marrow damage, and rheumatoid arthritis." (PMID 40943264, 2025). "We identified that PTPRS rs10415488 variant C shows features of neuroprotection against early Tau pathology and synaptic degeneration in Alzheimer’s disease." (PMID 38926456, 2024). "Herein, we sought to investigate the potential role of PTPRS single nucleotide polymorphisms (SNP) in the diverse stages of Alzheimer’s disease and identify potential links between the known functions of PTPRS, namely macroautophagy and synaptic plasticity, and the risk of developing AD." (PMID 38926456, 2024). "We examined the role of protein tyrosine phosphatase receptor sigma (PTPRS) in the context of Alzheimer’s disease and synaptic integrity." (PMID 38926456, 2024). "Our study thus suggests that PTPRS has protective effects against Tau pathology and synaptic destruction in the early phases of Alzheimer’s disease." (PMID 38926456, 2024). "Publicly available datasets (BRAINEAC, ROSMAP, ADC1) and a cohort of asymptomatic but “at risk” individuals (PREVENT-AD) were used to explore the relationship between PTPRS and various Alzheimer’s disease biomarkers." (PMID 38926456, 2024). "Overall, these results indicate that there exist a strong sexual bias in the production of PTPRS, which might act as a protective mechanism in men, who are known to be less prone to developing Alzheimer’s disease." (PMID 38926456, 2024). "We thus conclude that PTPRS acts as a neuroprotective receptor in Alzheimer’s disease." (PMID 38926456, 2024).
gout (2 papers, 2021 to 2025). A condition characterized by painful swelling of the joints, which is caused by deposition of urate crystals. "The results display a significant causal relationship between PTPRS and HUA in IVW analysis (p < 0.05, OR = 1.0457), which increases the risk of gout with increasing levels." (PMID 40430440, 2025). "Some research has found that PTPRS has been identified as the most up-regulated gene in gout patients." (PMID 40430440, 2025). "In addition, this study also found a causal relationship between PTPRS and HUA, providing more theoretical perspectives on the mechanism of Bi-Qi capsules in treating gout." (PMID 40430440, 2025). "PTPRS and DCLRE1C were identified as the most up-regulated and down-regulated genes in gout patients respectively." (PMID 35116032, 2021).
malignant peripheral nerve sheath tumor (2 papers, 2021 to 2022). Malignant peripheral nerve sheath tumor (MPNST) is a rare and often aggressive soft tissue sarcoma occurring in a wide range of anatomical sites. "As for PTPRS, it has been proved that reduced expression of PTPRS is significantly associated with the poor prognosis of esophageal squamous cell carcinoma and malignant peripheral nerve sheath tumor." (PMID 34194501, 2021).
rheumatoid arthritis (2 papers, 2025). A chronic, systemic autoimmune disorder characterized by inflammation in the synovial membranes and articular surfaces. "Inactivation of receptor PTP sigma (PTPRS) by HSPGs promotes the aggressive behavior of fibroblast-like synoviocytes (FLS) in rheumatoid arthritis (RA)." (PMID 40651610, 2025). "The soluble proteoglycan-binding ectodomain of PTPRS functions as a decoy for proteoglycan switch for the inhibition of invasiveness of synoviocytes in rheumatoid arthritis." (PMID 40943264, 2025).
Stroke (2 papers, 2023 to 2025). Sudden impairment of blood flow to a part of the brain due to occlusion or rupture of an artery to the brain. "The peptide resembling the wedge region of PTPRS, contributing to the dimer-induced activity inhibition, has therapeutic effects for stroke, multiple sclerosis, and spinal cord injury." (PMID 40943264, 2025). "Investigations of PKP4, DLG1, DLG2, PTPRS and OBSL1 found insufficient evidence to provide a direct link between these genes and neurodegenerative or stroke events." (PMID 37422595, 2023).
type 2 diabetes (2 papers, 2022 to 2023). "Several PTPs, such as PTPN1, PTPN2, PTPN9, PTPN11, PTPRS, and DUSP9, disrupt insulin signaling and trigger type 2 diabetes, indicating that PTPs are promising drug targets for the treatment or prevention of type 2 diabetes." (PMID 35204821, 2022). "Diverse PTPs, such as PTPN1, PTPN2, PTPN9, PTPN11, PTPRS, and DUSP9, have been reported to attenuate insulin signaling and trigger type 2 diabetes, indicating that PTPs are promising drug targets for the treatment or prevention of type 2 diabetes." (PMID 35204821, 2022). "Some PTPs, such as PTPN1, PTPN2, PTPN9, PTPN11, PTPRS, and DUSP9, have been shown to attenuate insulin signaling and trigger type 2 diabetes, indicating that PTPs are promising drug targets for the treatment or prevention of type 2 diabetes." (PMID 35204821, 2022).
amyloid (1 paper, 2024). "On the other hand, tissue PTPRS mRNA levels are decreased in cortical areas of AD patients compared to controls in APOE4-positive subjects, when the end-stage brains are saturated with both amyloid and Tau deposits." (PMID 38926456, 2024).
amyotrophic lateral sclerosis (1 paper, 2021). Amyotrophic lateral sclerosis (ALS) is a neurodegenerative disease characterized by progressive muscular paralysis reflecting degeneration of motor neurons in the primary motor cortex, corticospinal tracts, brainstem and spinal cord. "Although no brain pathologies have been causally linked to PTPRS mutations or impaired function, in a rat model of Amyotrophic lateral sclerosis (ALS), reduced neuronal expression of PTPRS has been observed." (PMID 34966732, 2021).
biliary tract cancer (1 paper, 2019). "Although we were not able to show direct effects of miR-145-5p on PTPRF or PTPRS, our results suggest an important functional role of miR-145-5p in biliary tract cancer and clearly demonstrate the activation of STAT1 signaling by miR-145-4p." (PMID 30886199, 2019).
brain tumor (1 paper, 2025). "Since only one brain tumor is considered pathognomonic for PHTS, a benign dysplastic tumor of the cerebellum known to be a hamartoma called Lhermitte–Duclos disease, it begs the question: could one of the subgroups of PTPRs be more characteristic of a hamartoma forming early in development?" (PMID 40136376, 2025).
colorectal tumors (1 paper, 2008). "Two genes, PTPN21 and PTPRS, were most frequently affected in primary colorectal tumors (16% and 12%, respectively)." (PMID 19000305, 2008).
depressive disorder (1 paper, 2024). A melancholy feeling of sadness and despair. "Interestingly, three other tyrosine phosphatase protein receptor genes (PRPRR, PTPRD, and PTPRS), were found to be significantly associated with depressive disorder." (PMID 38555957, 2024).
ependymoma (1 paper, 2025). A WHO grade II, slow growing tumor of children and young adults, usually located intraventricularly. "Diagnostic methods reported for PTPRs appear to be widely variable, lacking consensus for characteristics beyond imaging and histological appearance and immunohistochemical staining, which overlap closely with other primary CNS tumors, such as ependymomas." (PMID 40136376, 2025).
epidermoid carcinoma (1 paper, 2018). "PTPRS was reported to be an EGFR phosphatase in A431 epidermoid carcinoma cells and head and neck cancers." (PMID 29915291, 2018).
gastric cancer (1 paper, 2020). A primary or metastatic malignant neoplasm involving the stomach. "To explore key PTPRs that affect gastric cancer prognosis, we performed Cox regression analyses for all PTPR members with patients' survival data in TCGA databases." (PMID 32201537, 2020).
glioma (1 paper, 2023). A benign or malignant brain and spinal cord tumor that arises from glial cells (astrocytes, oligodendrocytes, ependymal cells). "Nevertheless, the NGS genes PTPRS, MAP2, and CADM1 were expressed in most malignant cells across these gliomas, consistent with the observed neurological associations of these genes." (PMID 37693314, 2023). "The most notable lncRNA is LINC00599, which has DBSs in many NGS genes in most gliomas, including GABBR1, NRCAM, PTPRS, GLRB, GRIA4, GRIK3, and MAP2, and the most notable NGS gene is MAP2, which is associated with microtube assembly and regulated by multiple lncRNAs through the same DBS." (PMID 37693314, 2023).
Hydrocephalus (1 paper, 2020). Hydrocephalus is an active distension of the ventricular system of the brain resulting from inadequate passage of CSF from its point of production within the cerebral ventricles to its point of absorption into the systemic circulation. "Although some variation and severity were observed, knockdown of the corresponding six genes (BMPR2A, BMPR2B, TFRC, F11R, PTPRS, and PGRMC2) resulted predominantly in ciliopathic disorders, including abnormal development, hydrocephalus, kidney cysts, and left–right asymmetry in cardiac looping." (PMID 32832346, 2020).
Insulin resistance (1 paper, 2023). Increased resistance towards insulin, that is, diminished effectiveness of insulin in reducing blood glucose levels. "Several protein tyrosine phosphatases (PTPs), particularly PTPN1, PTPN2, PTPN6, PTPN9, PTPN11, PTPRS, and DUSP9, are involved in insulin resistance." (PMID 37374154, 2023).